DSP (desmoplakin)
Diseases named in the same sentence as DSP in open-access papers (continued):
Sharing a sentence is not in itself a finding about the gene and the disease.
myocarditis (continued). "The incidence of potentially harmful mutations in the genes DSP, PKP2, and TNNI3 (encoding, respectively, desmoplakin, plakophilin-2, and troponin I type 3) is elevated in children with acute myocarditis." (PMID 37456487, 2023). "Interestingly, the authors found myocarditis-like episodes to be associated with HF and ventricular arrhythmic events, and hypothesized that acute myocardial injury episodes could play a role in the development of LV fibrosis and dysfunction in DSP carriers." (PMID 37048743, 2023). "For those carrying the DSP variant, all laboratory tests, including TnI and CRP, were performed in a stable phase as part of this study, and for patients with myocarditis, the test were conducted during the period of hospitalization." (PMID 37008330, 2023). "Homozygous variants in CMP disease genes such as desmoplakin (DSP) and troponin I3 (TNNI3) were identified in pediatric patients with myocarditis." (PMID 35877578, 2022). "The critical role of genetic (L)P variants in DSP and TNNI3 was replicated in several studies involving children or adults with myocarditis." (PMID 35877578, 2022). "Recently, LVNC induced by DES and DSP mutations was common and young-onset with HCM, DCM, ACM, myocarditis and HF, complicating ventricular and atrial tachycardias, and even needed therapy of heart transplantation in some cases." (PMID 34819141, 2021). "A recent study suggested clinical myocarditis as an initial ACM presentation proposing that these patients have distinct characteristics including female gender, LV involvement and DSP gene variants." (PMID 34988129, 2021). "A recent study further associated women being especially vulnerable to the initiating presence of clinical myocarditis in ARVC that harbored left ventricular involvement and prevalence of pathogenic DSP variants." (PMID 34765046, 2021). "A recent study reported on monozygotic twins who presented with myocarditis at ages 17 and 18; further investigation found extensive LGE pattern only involving the LV and a DSP variant in both twins." (PMID 32927679, 2020). "Patients with acute myocarditis and desmoplakin mutations were selected for the absence of major or minor imaging criteria for arrhythmogenic cardiomyopathy according to the Task Force criteria revised in 2010." (PMID 39336825, 2024). "Additionally, there has been greater recognition that some individuals diagnosed with acute or recurrent myocarditis carry aggressive ACM mutations, most notably DSP variants." (PMID 39763850, 2024). "The aim of this review is to describe the state of knowledge on the role of genetic background in myocarditis, with a specific focus on the clinical and molecular link/overlap with ACM, and in particular the major role played by DSP variants to explain this link." (PMID 39336825, 2024). "Based on the available data, the role of DSP in myocarditis, DCM, and ACM is intriguing." (PMID 39336825, 2024). "In patients presenting with acute myocarditis, a ring-like and septal LGE pattern was more common in patients later found to have a pathogenic or likely pathogenic variant in a desmosomal gene, most commonly DSP." (PMID 38137480, 2023). "The study population of participants with the DSP variant, family members without the DSP variant, and patients with myocarditis was small." (PMID 37008330, 2023). "A recent study reported variants in the DSP and DSG2 genes in six probands with familial myocarditis, allowing subsequent identification of up to 28 gene variant carriers, 39% of whom had a phenotype consistent with LV rather than classic right ventricular (RV) ACM." (PMID 37189393, 2023). "Echocardiography was conducted on all 29 patients with the DSP variant (9 index patients and 20 family members), 5 family members without the DSP variant, and 14 patients with myocarditis." (PMID 37008330, 2023).
myocarditis (continued). "NSVT was observed in 4/9 index patients, 3/20 family members with the DSP variant, 1/5 family member without the DSP variant, and 2/15 myocarditis patients." (PMID 37008330, 2023). "Similarly, in our cohort from Padova, 15% of DSP carriers presented episodes of clinically suspected myocarditis during a mean follow-up of 11 years." (PMID 37048743, 2023). "They found seven patients who had previously presented with acute myocarditis (one being from the phenotype-negative group); five of these patients carried DSP variants and all of these patients were relatives from a single ancestor." (PMID 32927679, 2020). "In this report, genotype-positive patients (89% DSP variant carriers) had a significantly higher incidence of the main endpoint (death, ventricular arrhythmias, recurrent episodes of myocarditis and heart failure) than genotype-negative individuals (62.3% vs. 17.5% at 5 years, p < 0.0001)." (PMID 37048743, 2023). "Interestingly, a recent European study was carried out, whereby genetic evaluations were performed on 336 consecutive patients with acute myocarditis—a P/LP variant in ACM- or DCM-associated genes was found in 8% of cases, and desmosomal mutations, mostly DSP truncating variants, were found in 3%." (PMID 37048743, 2023). "No other individual ACM gene demonstrated a statistically significant association, but the signal was not solely attributable to DSP because truncating variants in the other 4 ACM genes were also enriched in myocarditis cases in aggregate (PFisher=0.039; ∆+1.4%)." (PMID 36154167, 2022). "In another study, genetic analysis on three cases of myocarditis-related SCD and their family members revealed the presence of rare novel variants predicted as deleterious and potentially pathogenic in ACM-related genes (PKP2, DSP DSC2, and TTN), also including DSP as a crucial gene involved." (PMID 34988129, 2021). "Future prospective studies will help to decipher the natural history of morphofunctional and structural alterations in DSP-ACM, their relations with intercurrent events such as myocarditis episodes, and most importantly their prognostic significance in both quantitative and qualitative terms." (PMID 40021092, 2025). "Eight family members with the DSP variant presented with no LGE, whereas all index patients and all patients with myocarditis presented with LGE." (PMID 37008330, 2023). "All index patients and patients with myocarditis presented with substantial LGE, whereas some family members with the DSP variant had none." (PMID 37008330, 2023). "We evaluated whether immune activation in DSP–/– EHTs could be further stimulated by exposing EHTs to known activators of the TLR system to model myocarditis, albeit without lymphocytes and macrophages and as a means to examine the cardiomyocyte features that may underlie this process." (PMID 38768074, 2024).
arrhythmogenic right ventricular cardiomyopathy (31 papers, 2010 to 2026). "While the desmoplakin (DSP) gene is primarily associated with arrhythmogenic right ventricular cardiomyopathy (ARVC) and dilated cardiomyopathy (DCM), its role in HCM has been less frequently documented." (PMID 41561115, 2025). "Variants in the desmoplakin (DSP) gene have been recognized in association with the pathogenesis of arrhythmogenic right ventricular cardiomyopathy (ARVC) for nearly 20 years." (PMID 35083019, 2022). "The majority of pathogenic DSP mutations were frequently found as homozygous or compound heterozygous mutations in patients presenting arrhythmogenic right ventricular cardiomyopathy (ARVC) in combination with wooly hair and palmoplantar keratoderma." (PMID 33478057, 2021). "Mono-allelic dominant mutations in the desmoplakin gene (DSP) have been linked to known cardiac disorders, such as arrhythmogenic right ventricular cardiomyopathy and dilated cardiomyopathy." (PMID 33207704, 2020). "Previously mutations in the desmoplakin (DSP) gene have been associated with arrhythmogenic right ventricular cardiomyopathy (ARVC) and more recently with DCM." (PMID 32005173, 2020). "The model is shared amongst diverse linker domains and can be used to investigate the effects of pathogenic mutations in the desmoplakin linker associated with arrhythmogenic right ventricular cardiomyopathy." (PMID 32081916, 2020). "Mutations in DSP have been found in patients with arrhythmogenic right ventricular cardiomyopathy and DCM." (PMID 28934278, 2017). "Mutations in desmoplakin and plakophilin-2, two genes encoding desmosomal components expressed in the heart, have been implicated in the development of arrhythmogenic right ventricular cardiomyopathy (ARVC)." (PMID 20585603, 2010). "In contrast, the desmoplakin (DSP) gene, encoding the primary component of desmosomes, has been predominantly associated with arrhythmogenic right ventricular cardiomyopathy (ARVC) and dilated cardiomyopathy (DCM), with limited evidence supporting its role in HCM pathogenesis." (PMID 41561115, 2025). "We divided the AC patients into two groups, DPC carrying DSP gene mutations (nine patients from two different families) and arrhythmogenic right ventricular cardiomyopathy (ARVC) carrying PKP2 gene mutations (six patients from six different families) as per the recent report." (PMID 37450050, 2023). "Two of them were described before: DSP variant as unclassified in proband with arrhythmogenic right ventricular cardiomyopathy and MYH7 variant as possibly pathogenic but coexisting with another possibly pathogenic variant in LDB3 gene in proband with familial dilated cardiomyopathy." (PMID 28045975, 2017). "Cardiomyopathy caused by DSP mutations is usually associated with arrhythmogenic right ventricular cardiomyopathy (ARVC) or DCM." (PMID 39959410, 2025). "Genetic variation in DSP has been causally implicated in arrhythmogenic right ventricular cardiomyopathy (ARVC), with more recent suspicion in the pathogenesis of ALVC." (PMID 35083019, 2022). "Desmoplakin mutations cause the skin disorder disease striate palmoplantar keratoderma and arrhythmogenic right ventricular cardiomyopathy (ARVC), with the plakin domain being a hotspot with multiple identified pathogenic mutations." (PMID 23922795, 2013). "These genes are generally linked to arrhythmogenic right ventricular cardiomyopathy (ARVC), but recent evidence has correlated some of them (such as desmoplakin [DSP]) to biventricular cardiomyopathy as well." (PMID 37373876, 2023). "The presence of multiple pathogenic variants in desmosomal genes (DSC2, DSG2, DSP, JUP, and PKP2) in patients with arrhythmogenic right ventricular cardiomyopathy (ARVC) has been linked to a severe phenotype." (PMID 37418234, 2023).
arrhythmogenic right ventricular cardiomyopathy (continued). "In their study of 252 patients diagnosed with arrhythmogenic right ventricular dysplasia (ARVD) and a positive genetic mutation for DSP, Gasperetti and colleagues demonstrated that 37.3% of patients experienced a ventricular arrhythmic event following a follow-up period of at least 44.5 months." (PMID 40361967, 2025). "DSP mutation, being associated with arrhythmogenic right ventricular cardiomyopathy, was detected as well in one RCM patient, which is never reported in RCM cases previously." (PMID 31064352, 2019). "An array of mutations in desmoplakin PRD's have been mapped and may contribute to arrhythmogenic right ventricular cardiomyopathy (ARVC) pathogenesis." (PMID 26935805, 2016). "Arrhythmogenic right ventricular cardiomyopathy (ARVC) is a rare but severe cardiac condition frequently associated with mutations of proteins involved in desmosomes (Plakophilin-2, Desmoplakin, Desmoglein-2, and Desmocollin-2), structures involved in the cell–cell interactions." (PMID 33329039, 2020). "Genetic variants in desmosomal proteins (e.g., PKP2, DSP, DSG2, DSC2) are strongly associated with arrhythmogenic right ventricular cardiomyopathy (ARVC), while mutations in sarcomeric and cytoskeletal genes (e.g., MYH7, LMNA, DES) are linked to hypertrophic and dilated cardiomyopathies." (PMID 41596321, 2026).
dilated cardiomyopathy (31 papers, 2011 to 2025). Cardiomyopathy which is characterized by dilation and contractile dysfunction of the left and right ventricles. "Truncating mutations in the Ttn gene, responsible for encoding TITIN, a vital sarcomere component, and the Dsp gene, encoding Desmoplakin, both significantly impact the onset of dilated cardiomyopathy (DCM)." (PMID 38529333, 2024). "Palmoplantar keratoderma can indicate the presence of dilated cardiomyopathy (DCM) linked with a desmoplakin (DSP) mutation at an early stage." (PMID 39200108, 2024). "In Ecuador, the group of dermatologists Carvajal–Huerta found a recessive mutation of desmoplakin (DSP) in a family with dilated cardiomyopathy and cardiocutaneous syndrome." (PMID 37509658, 2023). "The first description of a myocardial disease linked to DSP mutations referred to patients with Carvajal syndrome, an autosomal recessive cardio-cutaneous syndrome, including dilated cardiomyopathy (DCM), palmoplantar keratoderma and wooly hair." (PMID 37048743, 2023). "Carvajal syndrome is a rare variant of Naxos disease, a recessive mutation of the desmoplakin gene characterized by presence of woolly hair, palmoplantar keratoderma and dilated cardiomyopathy, mainly left ventricular involvement." (PMID 35210635, 2022). "Human genetic mutation of the DSP gene results in several diseases, including dilated cardiomyopathy, keratoderma, and tooth agenesis." (PMID 36423088, 2022). "Some special gene mutations in dilated cardiomyopathy such as DSP, LMNA, SCN5A, and FLNC have an arrhythmia rate of more than 30%35." (PMID 31953454, 2020). "Mutations to the DSP gene, encoding desmoplakin, represent another condition co-existing between the arrhythmogenic and dilated cardiomyopathy spectrum, associated with high rates of ventricular arrhythmia and SCD with or without left ventricular dysfunction." (PMID 32648053, 2020). "DSP mutation may result in recurrent left ventricular (LV) inflammation and myocardial injury, leading to myocardial fibrosis, dilated cardiomyopathy, or arrhythmogenic cardiomyopathy (ACM)." (PMID 39336825, 2024). "DSP variants have been linked to arrhythmogenic and dilated cardiomyopathies, suggesting that this pathogenic DSP variants may have contributed to the decedent’s sudden death, although the association of DSP truncations with young sudden death is less well established." (PMID 38229148, 2024). "Erythrokeratodermia cardiomyopathy (EKC) syndrome is a rare autosomal dominant disorder characterized by generalized erythrokeratoderma and progressive dilated cardiomyopathy, caused by pathogenic variants in the SR6 domain of desmoplakin (DSP)." (PMID 41088746, 2025). "Since then, several reports have linked the DSP gene to familial forms of arrhythmogenic (ACM) and dilated cardiomyopathies." (PMID 37048743, 2023). "Variants in desmoplakin gene (DSP MIM *125647) have been usually associated with Arrhythmogenic Cardiomyopathy (ACM), or Dilated Cardiomyopathy (DCM) inherited in an autosomal dominant manner." (PMID 36768812, 2023). "Variants of uncertain significance (VUS) were found in 17 cases (eight resuscitated and nine dead) in genes associated with HCM or dilated cardiomyopathy (DCM), such as TTN, TNNT2, MYH6, DSP, ACTN2, CALR3, and MYH7." (PMID 36588553, 2022). "Desmoplakin haploinsufficiency was suggested to be associated with keratosis palmoplantaris striata II (PPKS2; OMIM #612908), and recessive mutations in the DSP gene have been associated with skin fragility/woolly hair syndrome (OMIM #607655) and dilated cardiomyopathy (OMIM #605676)." (PMID 26174853, 2015). "For example, mutations in JUP, DSP, PKP2, DSG2, DSC2, CTNNA3, CDH2, or PLN (all of them more abundant in LV) predominantly lead to arrhythmogenic right ventricular cardiomyopathy, and mutations in MYH7, HSPB7, NEXN and MYPN (also all more abundant in LV) lead to dilated cardiomyopathy." (PMID 32291283, 2020).
dilated cardiomyopathy (continued). "We identified a participant with dilated cardiomyopathy and arrhythmia (MCHTB11), diagnosed with a homozygous 2-bp deletion in the DSP gene (DSP c.4246_4247del; p.Leu1416AsnfsTer23)." (PMID 40562874, 2025).
Carvajal syndrome (27 papers, 2008 to 2026). "DSP mutations in dermatology are primarily associated with Carvajal syndrome, a condition characterized by both cutaneous and cardiac manifestations." (PMID 41502835, 2026). "Genetic analysis, using polymerase chain reaction (PCR), revealed a missense mutation in the DSP gene, confirming the diagnosis of Naxos disease variant (Carvajal syndrome) in both patients." (PMID 40108711, 2025). "Carvajal syndrome has been primarily associated with mutations in the DSP gene, located on chromosome 6p24, which encodes the DSP protein." (PMID 40564888, 2025). "The first association between DSP genetic variants and the presence of a myocardial disease referred to patients with Carvajal syndrome." (PMID 37048743, 2023). "Homozygous truncating mutations located in the C-terminal region of the desmoplakin gene (DSP) are known to mainly cause Carvajal syndrome, an autosomal recessive syndromic form of arrhythmogenic cardiomyopathy with an extra-cardiac cutaneous phenotype." (PMID 37143080, 2023). "The genetic basis for the disease was first revealed by the study of autosomal recessive forms of the cardiocutaneous form of AC and demonstrated loss-of-function mutations in desmoplakin (DSP) (Carvajal syndrome) and plakoglobin (JUP) (Naxos disease)." (PMID 34236518, 2021). "As human DSP mutations also cause Carvajal syndrome in addition to isolated ACM, a spontaneous homozygous Dsprul mouse model deserves attention." (PMID 32670084, 2020). "DSP was the first gene found to be linked with the autosomal dominant form of ARVC/D, and recessive mutations of DSP are found in a cardiocutaneous disease called Carvajal syndrome." (PMID 31616612, 2019). "Moreover, recessive mutations in DSP have been observed in Carvajal syndrome, a condition characterized by palmoplantar keratoderma, woolly hair, and biventricular dilated cardiomyopathy." (PMID 39600076, 2024). "The Carvajal syndrome is an autosomal recessive syndromic form of ACM (MIM#605676) with an extra-cardiac cutaneous phenotype mainly caused by homozygous truncating mutations located in the C-terminal region of DSP." (PMID 37143080, 2023). "Almost at the same time, Carvajal-Huerta and colleagues reported a homozygous truncating mutation in the DSP gene (encoding for desmoplakin) as causative of Carvajal Syndrome; a similar disease, characterized by biventricular cardiomyopathy, wooly hair, and PPK." (PMID 34950711, 2021). "Autosomal dominant is the most common pattern of inheritance in AC but desmosomal recessive forms have also been reported to present a cardio-cutaneous phenotype, named Naxos disease when JUP carries a homozygous mutation, and Carvajal syndrome when DSP carries a homozygous mutation." (PMID 33281612, 2020). "Consequently, desmoplakin (DSP) was associated with another autosomal recessive cardiocutaneous syndrome called Carvajal syndrome." (PMID 32899376, 2020). "The main difference between Carvajal syndrome and SFWHS lies in the location of the mutation within the DSP gene." (PMID 41502835, 2026). "Carvajal syndrome typically affects the C-terminal domain of desmoplakin, which binds intermediate filaments." (PMID 41502835, 2026). "Carvajal syndrome (CS, MIM # 605676) is another ultra-rare monogenic disease caused by pathogenic variants in the desmoplakin gene (DSP, OMIM # 125647)." (PMID 35200700, 2022). "Subsequently, genetic analysis revealed that another desmosomal gene, DSP, encoding for desmoplakin, harbored a homozygous truncating mutation in ACM in patients with a cardiocutaneous syndrome, named Carvajal syndrome." (PMID 31426283, 2019). "Subsequently, mutations of the desmoplakin (DSP) gene were found to cause another autosomal recessive cardiocutaneous syndrome, i.e. Carvajal syndrome." (PMID 27038780, 2016).